MIR548F3 (microRNA 548f-3)
Synonyms: hsa-mir-548f-3; MIR548F-3; MIRN548F3
Gene: MicroRNA gene on chromosome 5 (110,513,829 to 110,513,915, reverse strand). Ensembl gene ENSG00000221436.
Homologues: Orthologues: chimpanzee ptr-mir-548f-2 (100% identical). Paralogues in human: MIR548AZ (80% identical), MIR548F1 (78% identical), MIR548P (78% identical), MIR548H3 (75% identical), MIR548Z (75% identical), MIR548K (74% identical), MIR548AN (72% identical), MIR548AY (72% identical), MIR548AA1 (70% identical), MIR548X (70% identical), MIR548N (69% identical), MIR548X2 (69% identical), and 13 more.